EPO (erythropoietin)
Diseases named in the same sentence as EPO in open-access papers (continued):
Sharing a sentence is not in itself a finding about the gene and the disease.
Renal artery stenosis (4 papers, 2019 to 2024). The presence of stenosis of the renal artery. "Acquired erythrocytosis is often elicited by central or peripheral hypoxia resulting from cardiopulmonary disease/high-altitude dwelling or renal artery stenosis, respectively; EPO in the former instance is often normal (compensated by negative feed-back)." (PMID 34021251, 2021).
Secondary erythrocytosis (4 papers, 2022 to 2025). "Secondary erythrocytosis (SE) is a heterogeneous group of disorders primarily caused by the abnormal activation of EPO due to inadequate tissue oxygenation." (PMID 40502212, 2025). "Secondary erythrocytosis (SE) is a group of heterogeneous disorders, it is mainly caused by abnormal activation of the erythropoietin (EPO) in response to inadequate tissue oxygenation." (PMID 35304527, 2022). "A persistent challenge in clinical practice is differentiating PV from secondary polycythemia (SP), a reactive condition arising from physiological or pathological elevations in erythropoietin (EPO) levels." (PMID 41003014, 2025).
tuberculosis (4 papers, 2007 to 2024). A chronic, recurrent infection caused by the bacterium Mycobacterium tuberculosis. "This is due to the immune system's reaction to tuberculosis, which causes the release of cytokines that impair the body's capacity to use both stored iron and iron obtained from nutrition, as well as the creation and regular function of the hormone erythropoietin." (PMID 37868338, 2023).
Uterine leiomyoma (4 papers, 2014 to 2021). The presence of a leiomyoma of the uterus. "In order to confirm that the uterine leiomyoma was producing erythropoietin, the expression of erythropoietin in the tumor was investigated immunohistochemically." (PMID 24551466, 2014).
Ventriculomegaly (4 papers, 2018 to 2024). An increase in size of the ventricular system of the brain. "Despite these and other limitations, this novel model of PHHP and our initial findings using the clinically viable EPO+MLT treatment to prevent macrocephaly with ventriculomegaly, poor cliff aversion performance and associated microstructural abnormalities warrants additional investigation." (PMID 30319361, 2018). "To determine if EPO+MLT treatment impacted ventriculomegaly, we evaluated ventricular volume at P21." (PMID 30319361, 2018). "We developed a clinically relevant model of PHHP that exhibits essential components of PHHP, progressive macrocephaly with ventriculomegaly, and used this model to test whether extended EPO+MLT treatment can prevent the development of PHHP." (PMID 30319361, 2018). "We found that EPO+MLT prevented progressive macrocephaly and impaired cliff aversion performance, and reduced ventriculomegaly." (PMID 30319361, 2018). "In the EPO group, there were no cases (0.0%) of ventriculomegaly, while the No EPO group exhibited a 3.8% incidence (5 out of 130 neonates), resulting in a statistically significant difference with a p-value of 0.029." (PMID 38804373, 2024). "The incidence of ventriculomegaly was found to be similar in both groups, with an occurrence of 0.8% (1 out of 121) in the EPO group and 0.8% (1 out of 130) in the No EPO group, resulting in a non-significant p-value of 0.959." (PMID 38804373, 2024). "By contrast, 44% (4/9) of EPO+MLT-treated rats had a normal ventricular volume and only 11% had severe ventriculomegaly, a significant reduction in the proportion with ventriculomegaly compared to vehicle-treated CAM-IVH rats (Wilcoxon rank sum test, p = 0.005)." (PMID 30319361, 2018). "Using a strategy similar to EPO+MLT to induce multi-faceted repair, intravenous or intraventricular injection of umbilical-cord derived mesenchymal stromal cells on P6 improved early functional outcomes and reduced ventriculomegaly and GFAP-expression in rats with IVH on P4 or P5." (PMID 30319361, 2018).
acute lung injury (3 papers, 2014 to 2020). A condition of lung damage that is characterized by bilateral pulmonary infiltrates (pulmonary edema) rich in neutrophils, and in the absence of clinical heart failure. "The protective effect of EPO on AKI is very well-described; however, it is not for inflammasome, even reported in acute lung injury." (PMID 32414157, 2020).
acute respiratory distress syndrome (3 papers, 2011 to 2020). Progressive and life-threatening pulmonary distress in the absence of an underlying pulmonary condition, usually following major trauma or surgery. "Several reports exist demonstrating beneficial EPO effects on acute lung injury and the acute respiratory distress syndrome (ARDS) in various different animal models." (PMID 32546125, 2020).
aneurysm (3 papers, 2018 to 2024). Bulging or ballooning in an area of an artery secondary to arterial wall weakening. "Experimental aneurysm studies have mainly focused on endothelial cells, such as the autologous endothelial cell-seed stent and enhanced aneurysm neck endothelialization by erythropoietin-induced endothelial progenitor cell stimulation." (PMID 30555299, 2018). "Conversely, in the Conscious-I, EPO/Statin, I-HAST, MAPS, MASH1/2, and Utrecht clusters the majority (> 50%) of aneurysms were located at the ACOM and PCOM sites." (PMID 39118007, 2024).
Arrhythmia (3 papers, 2021 to 2025). Any cardiac rhythm other than the normal sinus rhythm. "RhEPO has been shown to significantly lower the occurrence of arrhythmias in this population by more than two-fold when comparing the EPO group to the placebo group." (PMID 35812547, 2022). "EPO administration in MI may reduce the incidence of post-MI arrhythmias, although larger RCTs are needed to confirm such therapeutic effects." (PMID 35812547, 2022). "However, EPO seems to reduce the incidence of post-MI arrhythmias." (PMID 35812547, 2022).
autism (3 papers, 2025). Persistent deficits in social interaction and communication and interaction as well as a markedly restricted repertoire of activity and interest as well as repetitive patterns of behavior. "Recent studies have examined EPO’s protective effects in propionic acid (PPA)-induced models of autism, reporting improvements following immediate post-insult EPO administration." (PMID 41284683, 2025). "We investigated whether postnatal treatment with DPO, a long-acting EPO analogue, could improve autism-relevant behaviors in a VPA rat model at an age roughly aligned with human ASD diagnosis." (PMID 41284683, 2025). "This study marks the first demonstration of the benefits of a non-erythropoietic EPO derivative for social behavior in a mouse model of autism and merits further investigation into the mechanisms by which this action occurs." (PMID 40137869, 2025).
autism spectrum disorder (3 papers, 2024 to 2025). A spectrum of developmental disorders that includes autism, and Asperger syndrome. "We demonstrate for the first time that an erythropoietin-derived compound can address social features of autism spectrum disorder in mice." (PMID 40137869, 2025). "We hypothesized that carbamoylated erythropoietin (CEPO) could rescue autism spectrum disorder (ASD)-related behaviors that appear in the BALB/cJ (BALB) mouse model." (PMID 40137869, 2025).
autonomic dysfunction (3 papers, 2016 to 2024). "A role has also been suggested for autonomic dysfunction through a relative or absolute imbalance in sympathetic/parasympathetic tone based on the hypothesis that EPO production may be modulated, in part, by the autonomic nervous system." (PMID 27142617, 2016).
bone marrow disorder (3 papers, 2017 to 2024). Any disease of the bone marrow. "The receiver operating characteristic curve analysis showed that an EPO cut-off value of 36.4 mU/mL had a sensitivity and specificity of 92.8% and 94.0% for detecting underlying bone marrow disease, respectively." (PMID 37741889, 2023). "In conclusion, the present study provides preliminary evidence for the potential diagnostic utility of EPO levels in identifying underlying bone marrow disease among elderly anemic patients with unclear etiology." (PMID 37741889, 2023). "This study aimed to investigate whether EPO levels could be used to identify underlying bone marrow diseases including malignancies, among elderly anemic patients with unclear etiology." (PMID 37741889, 2023). "At the EPO threshold of 25.0 mU/mL, all patients with bone marrow disease were correctly identified." (PMID 37741889, 2023). "We suggest measuring serum EPO levels can aid in the early detection of benign anemia from bone marrow disease, including malignancies, with high sensitivity and specificity." (PMID 37741889, 2023). "The ROC analysis demonstrated that an EPO level of 36.4 mU/mL had the highest sensitivity (92.8%) and specificity (94.0%) for detecting bone marrow disease." (PMID 37741889, 2023). "Other hypotheses have been described in previous papers, including bone marrow disorder, clonal hematopoiesis, poor renal function, and abnormalities of erythropoietin response, which could elevate the RDW value." (PMID 38541211, 2024). "We hypothesize that EPO levels could serve as a marker for detecting hidden bone marrow disease, including hematologic malignancies, in patients with AI or AUE." (PMID 37741889, 2023). "Second, EPO is not a specific marker for bone marrow disease and can be influenced by other factors such as renal function, hypoxia, recent bleeding, or hemolysis." (PMID 37741889, 2023). "Erythropoiesis can be impaired due to a lack of substrates needed for Hb synthesis (e.g., iron) or for cell division (e.g., vitamin B12 or folic acid), lack of erythropoietin (EPO) to stimulate erythropoiesis, or due to bone marrow disorders/aplasia." (PMID 27889956, 2017). "Besides a difference in EPO, RDW and MCV were higher in bone marrow disease group, which was consistent with previous reports, though RDW was not significantly different in the subgroup analysis, indicating that it may not be a reliable marker for detecting bone marrow disease in some cases." (PMID 37741889, 2023).
cataract (3 papers, 2012 to 2023). Partial or complete opacity of the crystalline lens of one or both eyes that decreases visual acuity and eventually results in blindness. "In conclusion, we found that, compared to the eyes with cataracts in the control group, the aqueous level of EPO is significantly higher in POAG, PXFG, and NVG eyes both with and without controlled IOP." (PMID 22876126, 2012). "In this prospective non-randomized comparative study, we report that the aqueous level of EPO is statistically significantly higher in eyes with POAG, PXFG, and NVG compared to age-matched eyes with only cataracts." (PMID 22876126, 2012).
chronic lung disease (3 papers, 2021 to 2024). According to the definitions of the American and British Thoracic Societies, including pulmonary functional tests, X-rays, and CT scans for items such as fibrosis, bronchiectasis, bullae, emphysema, nodular or lymphomatous abnormalities. "First EPO also trended higher for subjects with chronic lung disease." (PMID 34077474, 2021).
Chuvash polycythemia (3 papers, 2013 to 2019). Chuvash erythrocytosis is a rare, genetic, congenital secondary polycythemia disorder characterized by increased hemoglobin, hematocrit and erythropoietin serum levels and normal oxygen affinity, which usually manifests with headache, dizziness, dyspnea and/or plethora. "Rare congenital causes include hemoglobin mutations resulting in increased oxygen affinity, EPO receptor mutations, and mutations affecting regulation of EPO production by HIF, for example, Chuvash polycythemia." (PMID 24312736, 2013).
deficiency anemia (3 papers, 2018 to 2024). "Subcutaneous administration of recombinant EPO has been successfully used in the management of EPO-deficiency anemia in NS." (PMID 38393003, 2024). "The findings will help understand the mechanisms of EPO production in the kidney as well as EPO-deficiency anemia." (PMID 29535446, 2018).
developmental delay (3 papers, 2018 to 2021). "Thus, neonatal EPO+MLT treatment prevented progressive macrocephaly and early signs of developmental delay exhibited by vehicle-treated CAM-IVH rats." (PMID 30319361, 2018).
diabetic cardiomyopathy (3 papers, 2013 to 2021). Diabetic cardiomyopathy is a disorder of the heart muscle in people with diabetes. "EPO also prevented pathological changes in rats with diabetic cardiomyopathy by increasing the number of peripheral blood endothelial progenitor cells." (PMID 34339435, 2021). "Other therapeutic strategies such as the use of alpha lipoic acid or erythropoietin have been shown to inhibit TGF-β induced extracellular matrix accumulation in diabetic cardiomyopathy." (PMID 24886336, 2014).
diabetic macular edema (3 papers, 2010 to 2021). "EPO is present in considerably higher concentrations in eyes with diabetic macular edema than in eyes with exudative AMD or normal eyes." (PMID 34070383, 2021).
dilated cardiomyopathy (3 papers, 2012 to 2024). Cardiomyopathy which is characterized by dilation and contractile dysfunction of the left and right ventricles. "Despite this limitation, FDG-PET served for monitoring effects of EPO treatment on cardiac function in mice with virus-induced dilatative cardiomyopathy." (PMID 22863174, 2012). "Further workup showed dilated cardiomyopathy and low normal erythropoietin (EPO) levels." (PMID 39280364, 2024).
fungal infections (3 papers, 2007 to 2020). "The consequence of EPO pretreatment on fungal infection was determined by evaluating animal survival, fungal burden, activation of bronchoalveolar macrophages, inflammatory mediator release, and lung inflammation." (PMID 26538835, 2015). "Because of the importance of macrophages and lipid mediators for the control of fungal infection, the purpose of this study was to investigate the effect of EPO pretreatment in the progression of lung infection induced by Hc." (PMID 26538835, 2015). "Our results demonstrate for the first time that EPO treatment has a deleterious impact on lung immune responses during fungal infection." (PMID 26538835, 2015). "Considering that little is known about EPO's role during fungal infections and its capacity to activate macrophages, in this study we investigated the impact of EPO pretreatment on the alveolar immune response during Hc infection." (PMID 26538835, 2015). "Proof of principle for the potential of such intervention is shown by amphotericin B, a commonly used treatment for systemic mycoses, which enhances the interaction between HIF-1α C-terminal TAD and FIH-1, thereby blocking p300 recruitment and suppressing hypoxia-induced erythropoietin production." (PMID 18096060, 2007).
Graves disease (3 papers, 2017 to 2024). Graves' disease is an autoimmune disorder that leads to overactivity of the thyroid gland (hyperthyroidism).It is caused by an abnormal immune system response that causes the thyroid gland to produce too much thyroid hormones. "In addition, erythrocyte counts, serum erythropoietin, and hypoxia-inducible factor 1α levels patients with untreated Graves' hyperthyroidism were significantly higher than those in the age- and sex-matched healthy controls." (PMID 28910278, 2017).
hemangioma (3 papers, 2014 to 2016). A benign vascular lesion characterized by the formation of capillary-sized or cavernous vascular channels. "Similarly, the expression of the HIF-2α target gene EPO was dramatically increased (reactivated) in the livers of HA-positive LRRK2−/− mice, suggesting a close correlation of EPO expression and the formation of hemangiomas in LRRK2−/− mice." (PMID 27872856, 2016). "Hif-2α was found to mediate up-regulation of erythropoietin and multiple pro-angiogenic cytokines in these mouse models, and inactivation of Hif-2α or Hif-1β/Arnt, but not Hif-1α, rescued hemangiomas in PEPCK-Cre or Albumin-Cre driven Vhlh knockout mice." (PMID 27733136, 2016). "In this study, we report the identification of hemangioma-like growths in the livers of old LRRK2−/− mice and found that LRRK2 could affect the expression of EPO in the livers and kidneys of these mice." (PMID 27872856, 2016). "In livers of these hemangioma-positive LRRK2 knockout mice, we detected an increased expression of the HIF-2α protein and significant reactivation of the expression of the HIF-2α target gene erythropoietin (EPO), a finding consistent with a role of the HIF-2α pathway in blood vessel vascularization." (PMID 27872856, 2016).
hepatitis B (3 papers, 2011 to 2018). "Treatment with recombinant human erythropoietin was associated with increased antibody titers after hepatitis B vaccination in dialysis patients." (PMID 23326280, 2012). "Despite improvement in hepatitis B infection prevention through national vaccination programs, implementation of compulsory and thorough blood donor screening, and reduction of transfusion numbers due to erythropoietin administration,hepatitis B remains a major concern in hemodialysis (HD) centers." (PMID 22224080, 2011).
Hyperinsulinemia (3 papers, 2013 to 2021). An increased concentration of insulin in the blood. "Considering the positive association between fetal insulin levels and the incidence of later impaired glucose tolerance in the offspring, the correlation between AF EPO and offspring post-load PG concentrations in adulthood could be mediated by fetal hyperinsulinemia." (PMID 34777246, 2021).
Hypervolemia (3 papers, 2016 to 2022). An increase in the amount of intravascular fluid, particularly in the volume of the circulating blood. "Yet, in this study, it is noteworthy that the EPO increment in HBR was less than that detected in HAMB, despite the similar levels of PIO2 in the two confinements, suggesting that the bed rest‐induced central hypervolemia was still capable of blunting the hypoxia‐driven erythropoiesis." (PMID 27081163, 2016).
influenza (3 papers, 2017 to 2025). An acute viral infection of the respiratory tract, occurring in isolated cases, in epidemics, or in pandemics; it is caused by serologically different strains of viruses (influenzaviruses) designated A, B, and C, has a 3-day incubation period, and usually lasts for 3 to 10 days. "Some studies suggest that EPO may enhance the humoral response in fragile subjects vaccinated with influenza or hepatitis B vaccines." (PMID 40370459, 2025).
intrauterine growth restriction (3 papers, 2017 to 2021). "This study reports that the placental expression of EPO in human twin pairs is associated with fetal growth restriction and abnormal UA Doppler." (PMID 30089456, 2018). "We have previously reported that fetal plasma EPO concentrations were significantly increased in monochorionic (MC) twins with selective intrauterine growth restriction (sIUGR) and umbilical artery Doppler abnormality." (PMID 30089456, 2018).
ischemic disease (3 papers, 2017 to 2021). Lack of blood supply to an area of the body, resulting in impairment of tissue oxygenation. "GSK360A activation of the HIF pathway through PHD and the resulting secretion of the brain protective proteins (e.g., EPO and VEGF) that represent mixed mechanisms of action in the treatment of ischemic disease." (PMID 28880966, 2017). "Moreover, a study on ischemic disease in non-hematopoietic cells reported increased recovery of cell function through mitochondrial activity stimulation by an endogenous EPO inducer, indicating that EPO could be a potential therapeutic strategy for ischemic diseases." (PMID 33467745, 2021).